IL1B (interleukin 1 beta)
Diseases named in the same sentence as IL1B in open-access papers (continued):
Sharing a sentence is not in itself a finding about the gene and the disease.
COVID-19 (continued). "The excessive production of pro-inflammatory cytokines, such as IL-6, TNF-α, and IL-1β, leads to a cytokine storm, which is a key driver of the severe manifestations of COVID-19." (PMID 39130641, 2024). "Individuals who received dexamethasone had significantly lower levels of TNFα, IL6 and IL1β by 21–24 weeks in multivariable analyses, in contrast to findings at 9–12 weeks after COVID-19 onset." (PMID 39008486, 2024). "ER suppresses the transcription of several proinflammatory markers, such as TNF-α, IL-1β, and IL-12, suggesting its potential in regulating cytokine storms and consequently managing COVID-19." (PMID 39459194, 2024). "Inflammasome activation has been documented in COVID-19 patients with cardiac involvement, as shown by increased plasma levels of inflammasome markers including IL-1β, IL-1R antagonist (IL-1RA), IL-18 and IL-18-binding protein (IL-18BP)." (PMID 37251383, 2023). "One large study measured serum IL-1β in 1,715 hospitalized COVID-19 patients that included 1,959 measurements obtained at hospital admission." (PMID 37928695, 2023). "Severe COVID-19 patients had expanded IL-1β-expressing monocytes and macrophages in BALF and increased population of peripheral CD14+IL-1β+ monocytes and macrophages." (PMID 37251383, 2023). "The SARS-CoV-2 S protein is a surface-exposed viral receptor binding protein that can selectively trigger NLRP3 inflammasome activation and cytokine (e.g. IL-1β) secretion in macrophages derived from COVID-19 patients." (PMID 38090572, 2023). "For COVID-19, the most relevant conjectured location for tissue IL-1β bioactivity is within lung tissues." (PMID 37928695, 2023). "The levels of all analyzed interleukins, including TNF, IL-6, IL-1B, IL-8, IL-10, and IL-12p70, were significantly higher in the COVID-19 group compared to the control group." (PMID 37373613, 2023). "Our study showed that the level of IL-1β had been significantly associated with patient who need hospitalization, also the alteration of the level of miRNA-16–2-3P, miRNA-618 is positively correlated with the admission of these patients and influence the outcomes of SARS-cov-2 infection." (PMID 37222789, 2023). "The same increased tissue expression of IL-1β was observed in the COVID-19 compared to the CONTROL and H1N1 groups (p = 0.0002 and p = 0.0221, respectively)." (PMID 36992415, 2023). "We also assessed the proinflammatory cytokine (TNF-α, IL-6, and IL-1β) levels in RBD-treated cells as COVID-19 leads to a cytokine storm." (PMID 36982738, 2023). "COVID-19 patients treated with Tranilast had apparently lower levels of proinflammatory cytokines (e.g., IL-1β, IL-6 and TNF-α) than the controls." (PMID 37251383, 2023). "Another potent cytokine induced during the hyper-inflammatory state of COVID-19 is interleukin-1 beta (IL-1β)." (PMID 37427016, 2023). "During the COVID-19 phase, both IL1β and IL6 increased significantly at day 90 in Group I and showed no significant change in Group II." (PMID 37546047, 2023). "Recently, the hyperactivation of NLRP3 inflammasome followed by IL-1β was indicated as a potential regulatory factor in the pathogenesis of COVID-19, similar to other inflammatory diseases." (PMID 37685844, 2023). "Oher studies investigating immune features of COVID-19 convalescent trends observed elevated levels of IL-6 and IL-1β in individuals with PASC." (PMID 37077911, 2023). "We found that, at the time of treatment initiation, COVID-19 patients who responded to tocilizumab had higher levels of several pro-inflammatory cytokines, including IL-1β, IL-1α and IFN-β." (PMID 37215114, 2023). "Transcripts of genes encoding 6 biomarkers, IL-1β, IL-6, IL-10, C-reactive protein, IDO1 and ACE2, were measured by RT‒qPCR in saliva samples of patients and COVID-19-free individuals." (PMID 37715121, 2023).
COVID-19 (continued). "DEG analysis of IL1B/IL18+ COVID-19-infected BALF/lung versus IL1B/IL18+ control BALF/lung in the human, mouse, hamster, AGM, and ferret models showed host sDEGs and no viral sDEGs." (PMID 37737611, 2023). "In COVID-19 patients, plasma levels of pro-inflammatory cytokines, including interleukin (IL)-1α, IL-1β, and tumor necrosis factor α (TNF-α), are elevated, compared to healthy adults." (PMID 36671034, 2023). "In summary, we were able to establish an accurate model to early predict post COVID-19 symptomatology based on IL-1β, TNF-α and MIP-1α levels one month after the onset of the acute SARS-CoV-2 infection." (PMID 37894054, 2023). "The study showed that in both groups of patients, with OA and convalescent COVID-19, there was an increase in the plasma level of IL-1β and a decrease in TNF-α and NF-κB levels when compared to healthy controls." (PMID 37484856, 2023). "Evidence suggests that dysregulated inflammation with exacerbated production of inflammatory cytokines, such as IL-1β, IL-6, and IL-8, plays a significant role in patients with severe COVID-19." (PMID 37018291, 2023). "Is there empirical evidence suggesting existence of an occult IL-1β tissue reservoir that contributes to COVID-19 pathogenesis?" (PMID 37928695, 2023). "Our results indicate that patients recently recovered from mild and/or severe COVID-19 show semen inflammation as evidenced by elevated seminal plasma levels of IL-1β, TNF and IFNγ with respect to control individuals." (PMID 37497433, 2023). "Serum CCL2, CCL3, CCL7, CXCL9, CXCL10, IL-1β and IL-1Ra levels increased in critical COVID-19 patients (n = 11) when compared to both severe COVID-19 patients (n = 25) and moderate COVID-19 patients (n = 14)." (PMID 36941580, 2023). "Some studies have reported an elevation in the proportion of monocyte forming specks, increased caspase-1 activity, and heightened production of IL-1β and IL-18 from peripheral blood mononuclear cells (PBMCs) in COVID-19 patients." (PMID 38140660, 2023). "Our results show that the inflammasome signaling proteins IL-1β with an AUC of 0.91, and IL-18 with an AUC of 0.81 are the two most reliable biomarkers of the inflammatory response in COVID-19 among the inflammasome proteins analyzed in this study." (PMID 37168848, 2023). "Clusters 2 (n = 23) and 3 (n = 21) represent COVID-19 patients with the highest IL-1β (with low sRAGE and GDF15) and lactoferrin (and high Fec and GDF15), respectively." (PMID 37582864, 2023). "Severe COVID-19 cases are characterized by an increase in pro-inflammatory cytokines plasma levels, especially interleukins IL-1β, IL-2, IL-6, IL-7, and IL-10 granulocyte-macrophage colony-stimulating factor (GM-CSF) and tumor necrosis factor-alpha (TNF-a)." (PMID 37445296, 2023). "The concentrations of inflammasome-related markers, IL-1β, IL-18, gasdermin D, and lactate dehydrogenase, were significantly elevated in the serum and plasma of patients with COVID-19, compared with that of healthy donors." (PMID 36703213, 2023). "In men aged 35 years and older, we noted an increase in the proportion of sperm with fragmented DNA, higher concentrations of cytokines such as IL-1β and IL-10, and a decrease in the antioxidant defense of seminal plasma after COVID-19." (PMID 37958725, 2023). "The data obtained in the present study showed that patients with OA and those who recovered from COVID-19 6–9 months before had elevated plasma levels of IL-1β and decreased levels of TNF-α and NF-κB." (PMID 37484856, 2023). "Analysis of COVID-19 patients revealed heightened serum levels of IL-1β and IL-6, suggesting a pivotal role of these cytokines in the systemic inflammatory response associated with the disease." (PMID 37986089, 2023). "In human COVID-19, expression of IL1B and IL18 shifted from mostly alveolar macrophages to SPP1/MERTK+ macrophages." (PMID 37737611, 2023).
COVID-19 (continued). "Patients with critical COVID-19 have been found to have higher serum levels of Gal-3, along with increased proinflammatory cytokines (IL-1β, TNF-α, IL-12) and chemokine C-C chemokine receptor type 5 (CCR5) expression in T cells." (PMID 37298569, 2023). "In COVID-19-derived monocytes, TNFα, IL1β, IL6, IL10, CXCL8/IL8, and COX2 were also significantly increased, depending on disease severity." (PMID 37310504, 2023). "Several studies reported high levels of IL-1β and IL-1Ra in the peripheral blood and bronchoalveolar lavage fluid of COVID-19 patients." (PMID 37756264, 2023). "In severe cases, through inflammatory mediators like IFN-α, IL-1β, IL-6, CCL2, CCL5 and others, COVID-19 causes an inflammatory process that if uncontrolled evolves into lung tissue injuries, systemic inflammations and pathogenesis, and organ failure." (PMID 37662953, 2023). "Our results have allowed the design of a predictive model for post COVID-19 based on the levels of three cytokines at month 1 (IL-1β, TNF-α, and MIP-1α)." (PMID 37894054, 2023). "IL-1β induces the production of IL-6, another abundantly detected cytokine in severe COVID-19 patients." (PMID 36661317, 2023). "The lungs of patients with severe COVID-19 are abundant in highly inflammatory macrophages, which secrete inflammatory mediators like IL-1β, IL-6, IL-8, CXCL10, TNF-α, and other chemokines, further exacerbating the occurrence of cytokine storms." (PMID 37163438, 2023). "Accordingly, upregulation of these regulatory immune subtypes was associated with lower levels of proinflammatory cytokines, in particular IL-6 and IL-1β, in the blood of treated severe COVID-19 patients." (PMID 37833265, 2023). "Hyperinflammation is a hallmark of COVID-19 and is characterized by high levels of circulating proinflammatory cytokines, including interleukin-6 (IL-6), interferon-γ (IFN-γ), IL-1β, tumor necrosis factor (TNF), acute phase reactants, and ferritin." (PMID 38022199, 2023). "According to severity, it was seen that COVID-19 severe cases have lower production of IL1β at all times analyzed and of TNF at times 4/6 and 45/60 days." (PMID 37515295, 2023). "The PPI network revealed that IL-6, MAPK1, TNF, and IL1B were the main targets of bitter almond-licorice to interfere with COVID-19." (PMID 38018195, 2023). "Another notable finding was the elevated levels of IL-1β and IL-17 in the serum of severe COVID-19 patients compared to the control group." (PMID 37373331, 2023). "In the same way, in a recent study, it has been demonstrated that combination treatment with human monoclonal anti-IL-1β antibody, remdesivir, and steroids in moderate-to-severe hospitalized COVID-19 patients can reduce inflammatory markers." (PMID 37834421, 2023). "The overexpression of CRP, ferritin, LDH, TNF-α, IL-1β, IL-6, IL-2, IFN-γ, and vascular endothelial growth factor (VEGF) can be associated with COVID-19 severity." (PMID 37654571, 2023). "Among them, we can highlight the involvement of slc2a1a, slc2a1b (cell membrane glucose transport), interleukins- il1b, and il6 (pro-inflammatory pathway), nfkbiab, and coa1 (mitochondrial respiratory chain) in COVID-19." (PMID 37047078, 2023). "The administration of dexamethasone to critical COVID-19 patients was found to significantly reduce the plasma levels of inflammatory mediators including IL-1β, IL-6, IL-8, IL-10, and MIP-1α, and this to counteracted hyper-inflammation." (PMID 37631998, 2023). "The antiviral IFN-α and proinflammatory TNF, IL-6, IL-8, IL-17, IL-33, and IFN-γ were elevated in COVID-19 patients at both time points, while IL-10 and IL-1β were increased at admission and one week later, respectively." (PMID 37174682, 2023). "Herein, we demonstrated that COVID-19 patient–derived EVs or viral spike protein triggered-pEVs that carried miR-21/let-7b induced IL-1β/TNF-α/IL-8 upregulation in neutrophils by interacting with TLR7/8 to activate NF-κB." (PMID 37904132, 2023).
COVID-19 (continued). "Evidence from clinical studies indicates that the severity of COVID-19 is positively associated with chemokine and inflammatory cytokine levels in the plasma of patients, such as TNF-α, IL-1β, IL-6, CCL2, CCL8, and CXCL9." (PMID 38104081, 2023). "Consistent with previous studies, activated NLRP3 inflammasome, accompanied by IL-1β release, was observed in circulating monocytes from severe COVID-19 patients." (PMID 37251383, 2023). "Elevated proinflammatory cytokines such as IL-1β and IL-18 are characteristic of patients with severe COVID-19." (PMID 36703213, 2023). "On a similar note, IL-1β inhibitors have also been reported to play a substantial role in the prevention of COVID-19." (PMID 37446547, 2023). "Compared with the control group, there was extensive cytokine/chemokine correlations centered on IL-17A, IL-10, IL-6, CCL2, CXCL8, CXCL9 and CXCL10 and fewer correlations with IL-1β in the COVID-19 patients at baseline." (PMID 37662953, 2023). "Creatinine was positively correlated with INF-γ (r = 0.535, p = 0.001) in the post-COVID-19 female patients but negatively correlated with IL-1β (r = −0.546, p = 0.006) in the post-COVID-19 male patients." (PMID 37896963, 2023). "Our findings confirm a defined cytokine signature in severe COVID-19 (with elevated IL-2, IL-6, TNFα, IL-1β and IL-10), and add further evidence to the role of IP-10, G-CSF and IL-33 in the cytokine milieu associated with severe COVID-19." (PMID 37063871, 2023). "Serum levels of IL-1β, IL-6, IL-8, and TNF-α are elevated in COVID-19 patients and are associated with severe infection." (PMID 37376569, 2023). "Regarding the inflammatory response, TNF-α, IL-1β, IL-6, GM-CSF, IL-8, IL-4, and IL-10 are involved in BA to alleviate COVID-19, ALI, PF, COPD, PAH, and asthma." (PMID 37007037, 2023). "The causal association between PCT3 (Aggregatibacter actinomycetemcomitans), PCT5 (Porphyromonas gingivalis), and gingival crevicular fluid (GCF) interleukin-1β (IL-1β) and COVID-19 were considered." (PMID 36718446, 2023). "Among the genes most refractory to glucocorticoid treatment, CCL3 and IL1B stand out, both with a central role in the pathophysiology of COVID-19 and highly expressed in peripheral blood mononuclear cells during the disease." (PMID 36993968, 2023). "IL-8 has been suggested as a target for anti-cancer drugs and has been associated with adverse outcomes in COVID-19 patients, along with TNF-α, IL-6, IL-1β, and IL-33." (PMID 37627815, 2023). "Analysis of COVID-19 patients revealed increased microglial activation and IL-1β expression compared with the control group." (PMID 36672177, 2023). "To date, a number of IL-1β blockers have been investigated by the FDA for the treatment of COVID-19." (PMID 37446547, 2023). "In fact, we detected semen inflammation in patients recently recovered from mild and/or severe COVID-19 as shown by increased levels of IL-1β, TNF and IFNγ in seminal plasma." (PMID 37497433, 2023). "Serum IL-1β was measured in 46 COVID-19 patients in intensive care (median 0.35 pg./mL), in 30 COVID-19 patients not in intensive care (median 0.32 pg./mL), and in 24 healthy volunteers (median IL-1β 0.11 pg./mL)." (PMID 37928695, 2023). "Elevated levels of plasma IL-1β, IL-6, and TNF were shown to be associated with postacute sequelae of COVID-19." (PMID 37228441, 2023). "A single study reported that in COVID-19 cases, high serum IL-1β and IL-6 in the disease were correlated with critical in-hospital deaths (p = 0.01)." (PMID 37106750, 2023). "Regarding COVID-19, eight studies showed increased IL-1β, IL-6, and TNF-α in these cases compared to the controls, five studies showed elevated IL-6 alone, and one study indicated higher TNF-α alone." (PMID 37106750, 2023). "When the COVID-19 group was subdivided, only long-COVID-19 showed significantly higher IL-1β and IL-6 SARS-CoV-2 S protein-specific values compared to healthy individuals." (PMID 37018291, 2023).
COVID-19 (continued). "Patients infected with COVID-19 have high levels of IL-1β, IFN-γ, IP-10/CXCL10, and MCP-1/CCL2, leading to activated T-helper-1 (Th1) cell responses." (PMID 36851766, 2023). "Monocytes from HD + COVID-19 patients showed an enhanced capacity for pro-inflammatory cytokine production, with GM-CSF, IL-1β, IL-8, IL-10, CCL2 and CCL3 as the most increased cytokines compared with uninfected HD patients." (PMID 36675231, 2023). "Given the important role of IL-1β in the cytokine storm, several agents targeting IL-1β signaling, including canakinumab and anakinra, have been introduced to clinical COVID-19 treatment trials." (PMID 36793739, 2023). "We detected an increase in the relative expression of the IL-6, CRP, ACE2 and IL-1β biomarkers of 2 mild cases and one moderate case with long COVID-19 compared to healthy individuals." (PMID 37715121, 2023). "In 118 hospitalized COVID-19 patients (78% considered severe), 0.11 pg./mL median IL-1β was measured in plasma." (PMID 37928695, 2023). "This is also shown by the low increases of blood IL-1β levels in most patients in this cohort and by the low IL-1β increments in COVID-19 found by other authors." (PMID 37215142, 2023). "Available evidence has verified that COVID-19 patients had increased serum levels of proinflammatory cytokines, such as IL-1β, IL-6 and IL-10, alluding to the implication of a cytokine storm." (PMID 37251383, 2023). "IL-1β concentration was significantly increased only in the COVID-19 female patients at diagnosis (p < 0.05)." (PMID 37896963, 2023). "Because COVID-19 causes a cytokine storm by increasing pro-inflammatory cytokines such as TNF-α, IL-6, and IL-1β, we also analyzed these cytokine levels in the media of cells treated without or with the RBD for 24–120 h." (PMID 36982738, 2023). "The increase in systemic IL-1β and IL-18 levels is in accordance with other reports in critical COVID-19 patients." (PMID 37582864, 2023). "Observational studies showed elevated levels of different cytokines in COVID-19 patients, such as TNFα, IL-1β, IL-6, IL-8, IL-10, and IL-17." (PMID 36983830, 2023). "The serum IL-6, IL-8, TNF-α, and IL-1β levels were reported to be elevated in hospitalized patients with COVID-19." (PMID 36864432, 2023). "In COVID-19, there was a strong positive correlation between Gal-3 and interleukin-1 beta (IL-1β), as well as a moderate positive correlation between Gal-3, TNF-α, and IL-12, indicating a T-helper 1 (Th1) immune response." (PMID 37298569, 2023). "When COVID-19 progresses to severe illness, higher serum levels of IL-6, CXCL8, TNF-α, and IL-1β are associated with hyperinflammatory and hyper-coagulable conditions." (PMID 37908356, 2023). "In COVID-19 hearts, we identified significant upregulation of pro-inflammatory genes IL1B, IL-6, IL8, and the toll-like receptor TLR2." (PMID 36371548, 2023). "All of the 6 intersected genes have been reported to associate with COVID-19, including FGFR3, TP63, CXCL2, CCL20, IL1B and CXCL8." (PMID 37497545, 2023). "During COVID-19 progression, abnormal levels of IL-1β, TNF-α, IL-2, IL-7, IL-12, macrophage colony-stimulating factor (M-CSF), granulocyte colony-stimulating factor (G-CSF), and others can be detected in patient’s blood." (PMID 36702907, 2023). "Our data agree with another study that verified inflammatory profiles in COVID-19, demonstrating increases in serum levels of IL-1β, IL-6, IL-8, and TNF in patients with COVID-19 compared to healthy donors." (PMID 37018291, 2023). "Plasma IL-1β in hospitalized COVID-19 patients in China showed median level of about 1.5 pg./mL in 13 ICU patients and about 1.5 pg./mL in 27 non-ICU patients; 4 healthy control subjects had median levels of approximately 0.3 pg./mL." (PMID 37928695, 2023). "Clinical evidence suggests that patients with severe COVID-19 have markedly increased levels of pro-inflammatory cytokines within their bodies, including IL-1β, IL-2, IL-6, IL-7, IL8, TNF-α, CCL2, MIP-1α, and CXCL10." (PMID 37163438, 2023).